ELOA3P (elongin A3, pseudogene)
Synonyms: HsT829; TCEB3L2; ELOA3A; ELOA3AP; formerly TCEB3C; ELOA3
Gene: Processed pseudogene on chromosome 18 (47,028,202 to 47,029,842, reverse strand). Ensembl gene ENSG00000288631.
Genetic constraint (gnomAD): Missense variants: 0 observed, 72.33 expected, observed/expected ratio (o/e) 0, 90% interval 0 to 0.041. Synonymous variants: 0 observed, 25.69 expected, observed/expected ratio (o/e) 0, 90% interval 0 to 0.12.